PARG (poly(ADP-ribose) glycohydrolase)
Diseases named in the same sentence as PARG in open-access papers (continued):
Sharing a sentence is not in itself a finding about the gene and the disease.
renal carcinoma (2 papers, 2021 to 2022). A carcinoma arising from the epithelium of the renal parenchyma or the renal pelvis. "In conjunction to this, we have recently reported that the reduction of pADPr, by either pharmacological inhibition of PARP or PARG’s overexpression, disrupts renal carcinoma cell malignancy in vitro." (PMID 35585513, 2022). "Reduction of pADPr by PARP-1 inhibition or PARG overexpression disrupts renal carcinoma cell malignancy." (PMID 34638458, 2021).
triple-negative breast carcinoma (2 papers, 2019 to 2023). An invasive breast carcinoma which is negative for expression of estrogen receptor (ER), progesterone receptor (PR), and human epidermal growth factor receptor 2 (HER2).
African trypanosomiasis (1 paper, 2023). "Therefore, although it is likely that a PARP/PARG-mediated treatment is closer for Chagas disease, a similar achievement could be attained for African trypanosomiasis." (PMID 37242378, 2023).
bladder urothelial carcinoma (1 paper, 2020). "On the other hand, esophageal squamous cell carcinoma, cholangiocarcinoma, bladder urothelial carcinoma, thymic epithelial tumors and diffuse glioma show amplification of PARG gene, possibly suggesting the overexpression of PARG." (PMID 32344695, 2020).
Chagas disease (1 paper, 2013). A parasitic infection caused by Trypanosoma cruzi. "We conclude that both, T. cruzi and the host, poly(ADP-ribose) glycohydrolase activities are important players in the life cycle of Trypanosoma cruzi, emerging as a promising therapeutic target for the treatment of Chagas’ disease." (PMID 23776710, 2013).
clear cell adenocarcinoma (1 paper, 2021). A malignant neoplasm composed of glandular epithelial clear cells. "Next, we evaluated the expression of PARG mRNA in different histological subtypes using Meyniel dataset and found relatively higher expression levels of PARG mRNA in serous adenocarcinoma cases compared to other histological subtypes like endometrioid, mucinous, and clear cell adenocarcinoma." (PMID 34778062, 2021).
colitis (1 paper, 2019). Inflammation of the colon. "According to experimental models of colitis, the serum titre of antibodies against PARG is a marker of mucosal damage caused by refractory ulcerative colitis." (PMID 30991935, 2019). "As for PARP1, a murine experimental model of colitis shows the contribution of PARG in sustaining the inflammatory response in the colon." (PMID 30991935, 2019).
gastric cancer (1 paper, 2026). A primary or metastatic malignant neoplasm involving the stomach. "Here, we identify poly(ADP-ribose) glycohydrolase (PARG) as a regulator of p21 stability in gastric cancer (GC) cells." (PMID 41538291, 2026).
germ cell tumor (1 paper, 2020). A benign or malignant, gonadal or extragonadal neoplasm that originates from germ cells. "PARG inhibitors, in combination with DNA-damaging agents, may efficiently suppress tumor growth in particular types of germ cell tumors." (PMID 32344695, 2020). "This suggests that PARG might be an attractive therapeutic target in cancer control of germ cell tumors." (PMID 32344695, 2020).
HCMV infection (1 paper, 2022). "To explore the underlying mechanisms that regulate PARG expression after HCMV infection, we introduced UV-inactivated HCMV and phosphonoformic acid (PFA)." (PMID 36146855, 2022). "In the present study, we investigated the role of PARP-1 and PARG on HCMV infection and identified HCMV UL76 as a novel regulator of PARP-1 activity." (PMID 36146855, 2022). "In contrast to HCMV infection, PARG was downregulated in HSV-1-infected cells which was consistent with the previous study." (PMID 36146855, 2022). "To further confine the viral genes that are responsible for inducing upregulation of PARG during HCMV infection, we used the viral DNA synthesis inhibitor phosphonoformic acid (PFA)." (PMID 36146855, 2022). "We examined the mRNA level of PARG by RT-qPCR and found that PARG mRNA continuously increased after HCMV infection." (PMID 36146855, 2022). "In the context of HCMV infection, we found that HCMV infection upregulated the transcription of PARG in fibroblast, which was continuously increased from 12 hpi to 96 hpi." (PMID 36146855, 2022). "PFA (250 ug/mL) was applied to the cell in parallel with HCMV infection and the expression profile of PARG was analyzed by WB." (PMID 36146855, 2022). "Collectively, we explored the role of PARP-1 and PARG in HCMV infection and uncovered the relationship between HCMV and protein PARylation." (PMID 36146855, 2022). "As HCMV infection activated PARP-1 and induced the reposition of PARP-1, we want to know whether HCMV infection also affected the expression of PARG." (PMID 36146855, 2022). "Thus, we demonstrated that HCMV infection induced the upregulation of PARG." (PMID 36146855, 2022). "We initially employed Olaparib (PARPi) and pDD00017273 (PARGi), small molecular inhibitors against PARP-1 and PARG, respectively, to investigate the role of PARP-1 and protein PARylation on HCMV infection." (PMID 36146855, 2022). "Functionally, the inhibition of PARG after HCMV infection is beneficial to the production of HCMV, but does not affect the expression of type I interferon genes." (PMID 36146855, 2022).
invasive ductal carcinoma (1 paper, 2019). "Heightened PARG mRNA is five times more prevalent in invasive ductal carcinoma than invasive lobular carcinoma." (PMID 30459355, 2019). "On the other hand, 30% of the invasive ductal carcinoma tissues and 15% of lymph nodes metastases showed an intense PARG protein signal." (PMID 30459355, 2019).
lung adenocarcinoma (1 paper, 2013). A carcinoma that arises from the lung and is characterized by the presence of malignant glandular epithelial cells. "It was reported that poly(ADP-ribose) accumulation occurred after a PARG shRNA expression vector was stably introduced into A549 cells, a lung adenocarcinoma cell line." (PMID 23467693, 2013).
metastatic tumors (1 paper, 2022). "And yet, very little is known about the mechanisms of PARG regulation, its role in tumorigenesis, and molecular pathways that might be affected by PARG’s inhibition or activation in metastatic tumors." (PMID 35585513, 2022).
osteoporosis (1 paper, 2022). A condition of reduced bone mass, with decreased cortical thickness and a decrease in the number and size of the trabeculae of cancellous bone (but normal chemical composition), resulting in increased fracture incidence. "The development of novel PARG inhibitors for clinical use that can promote osteoblast differentiation will provide valuable therapeutic agents for metabolic bone diseases such as osteoporosis." (PMID 35563432, 2022). "Thus, PARG inhibitor administration could provide therapeutic benefits for metabolic bone diseases such as osteoporosis." (PMID 35563432, 2022).
osteosarcoma (1 paper, 2016). A usually aggressive malignant bone-forming mesenchymal neoplasm, predominantly affecting adolescents and young adults. "Similarly, other BRCA1-wild type cell lines tested, such as the non-tumour MCF10A breast cell line, the lung fibroblastic MRC5 cell line (data not shown) and the U2OS osteosarcoma cell line showed no particular sensitivity to PARG depletion." (PMID 27375368, 2016).
prostate adenocarcinoma (1 paper, 2019). "In prostate adenocarcinoma (PC3) and breast mammary epithelial (MCF-7) cells, PARG level was the highest in the cytoplasm, followed by the nucleus, with the lowest seen in the chromatin fraction." (PMID 31827085, 2019).
prostate tumors (1 paper, 2020). "In human prostate tumors, an AR and PARG functional interaction is supported by highly significant positive Spearman correlations between AR and PARG mRNA levels: r = 0.38, p = 1.00e-1755, r = 0.33, p = 5.30e-942, r = 0.41, p = 4.15e-21 (TCGA, Provisional)." (PMID 32123273, 2020).
psoriasis (1 paper, 2021). An autoimmune condition characterized by red, well-delineated plaques with silvery scales that are usually on the extensor surfaces and scalp. "Although no alteration in the expression profile of the gene encoding PARG was found, the transcript levels of the genes encoding several PAR hydrolases, namely MACROD1, MACROD2, and TARG1 were lower in psoriasis lesional skin." (PMID 34748530, 2021).
seizure disorder (1 paper, 2020). "Mutation of TARG1, the other enzyme that together with PARG removes PAR polymers from the target proteins, was indicated in a neurodegenerative and seizure disorder, and its deficiency sensitizes the cells to DNA alkylating agents." (PMID 32106627, 2020).
serous adenocarcinoma (1 paper, 2021). An adenocarcinoma that is characterized by the presence of papillary patterns and cellular budding. "We initially evaluated the PARG mRNA expression in normal ovarian samples compared to high grade serous adenocarcinoma samples using two different datasets of ONCOMINE database: the TCGA dataset (586 cases) and Hendrix dataset (41 cases)." (PMID 34778062, 2021).
serous cystadenocarcinoma (1 paper, 2021). A malignant serous cystic neoplasm usually involving the ovary or the pancreas. "Polβ/PARG co-expression was associated with serous cystadenocarcinomas (p = 0.017) and higher stage (p = 0.004)." (PMID 33674744, 2021). "High PARG expression was associated with serous cystadenocarcinomas (p = 0.011)." (PMID 33674744, 2021).
viral infection (1 paper, 2021). "Overall, the viral infection initiates a detrimental cycle of oxidative stress-mediated dysfunction, including PARP and PARG (macrodomain of the virus and host PARG) activities, ADP-ribose increase, TRPM2 activity, apoptosis and/or necrosis, and release of inflammatory mediators and vasodilators." (PMID 34064039, 2021).
cancer (73 papers, 2009 to 2026). A tumor composed of atypical neoplastic, often pleomorphic cells that invade other tissues. "Complementary to the use of PARPi for targeting HR deficiencies, PARG inhibitors seem to be useful to exploit deficiencies in the DNA replication machinery of cancer cells." (PMID 38360994, 2024). "We recognize that additional studies in multiple PDD00017273‐resistant human cancer cells using identified gene mutations such as PARG and PARP1 are required to comprehend the mechanisms of PDD00017273 resistance." (PMID 36053937, 2023). "It is plausible that the pathological events observed in PARG-depleted livers during early postnatal development predispose them to cancer development." (PMID 38139034, 2023). "Previous studies have examined the correlation between BRCA1/2 mutation and PARG inhibitor sensitivity in numerous cancer cells." (PMID 36053937, 2023). "And yet, while the expression of chemokines has been directly implicated in every stage of cancer development, the role of PARG in controlling cellular chemokines remains elusive and controversial." (PMID 35585513, 2022). "Preclinical and clinical efficacy of DDR inhibition in cells with a defective DDR genetic background, are exemplified by the success of PARP inhibitors in BRCA1/2-mutated advanced cancers and of inhibitors to the PARG in cancer cells." (PMID 34970273, 2021). "The cytoprotective role of PARG through its involvement in DNA repair in normal cells has been suggested, whereas the functional inhibition of PARG is reported to cause sensitization to DNA-damaging agents in cancer cells." (PMID 32344695, 2020). "Rather than synergizing with deficiencies in DNA repair pathways, PARG inhibitors seem to exploit deficiencies in replication machinery and higher levels of replication stress in cancer cells." (PMID 32029455, 2020). "PARG has been reported to be synthetically lethal (SL) with different genes that often undergo loss of function mutations in cancer, enabling targeted cell death." (PMID 33005627, 2020). "Importantly, loss of PARG expression has been identified as one of the PARPi resistance mechanisms, underscoring the potential of de-PARylation systems in modulating cancer cell drug responses." (PMID 39615107, 2025). "Targeting poly(ADP-ribose) glycohydrolase (PARG) is being explored as anti-cancer therapeutic strategy, and PARG loss may also contribute to resistance to PARP inhibitor (PARPi) treatment." (PMID 38360994, 2024). "However, the pronounced anomalies observed in early postnatal development due to PARG deficiency predispose liver tissue to various liver pathologies later in life, including the development of cancer." (PMID 38139034, 2023). "In addition, resistance to PARP inhibitor of BRCA1/2 mutated cancer is due to the lowered activity of endogenous PARG." (PMID 35447104, 2022). "In addition to PARP inhibitors, PARG inhibitors can exacerbate replication deficiencies and be considered promising therapeutic modalities against cancer types with genomic instability." (PMID 34638660, 2021). "However, recent genome sequencing approach accumulated the information of PARG gene mutations in various types of cancer." (PMID 32344695, 2020). "However, the underlying molecular mechanism in PARG mediated cancer development and progression is still elusive, which prohibits the possible clinical applications of PARG in cancer therapy." (PMID 27003318, 2016). "In addition, because PARG deficiency enhances cytotoxic sensitivity induced by chemotherapy agents, PARG inhibitors are potential anti-cancer drug sensitizers." (PMID 24465839, 2014). "Therefore, we tested whether the LNT1 inhibitor also kills human cancer cells carrying a PARG deficiency." (PMID 38360994, 2024).
cancer (continued). "Moreover, our finding that PARG expression may a potential biomarker of PARGi sensitivity will allow the further development of these inhibitors for the treatment of tumors with PARG loss and therefore offer a new targeted strategy for cancer therapy." (PMID 38578205, 2024). "Their involvement in PARP/PARG/mADPr metabolism makes them proteins of current therapeutic interest in metabolic diseases such as cancer or neurodegenerative diseases, thanks to their involvement in mitochondrial stability and function." (PMID 41463260, 2025). "We also performed Kaplan–Meier survival plots for PARG, showing overall survival curves in cancer patients with low and high PARG expression (data analysis and graphs from GEPIA3, p-value 0.0151)." (PMID 41463260, 2025). "For this review, we compared expression profiles for PARG between tumor versus normal tissues using the TCGA Pan-Cancer Atlas and obtained data analysis from GEPIA3." (PMID 41463260, 2025). "Despite ARH3 and PARG having epistatic molecular functions, genetic ARH3 loss sensitizes cancer cells to PARGi." (PMID 39615107, 2025). "Further mechanisms of PARP inhibitor resistance in BRCA-mutated cancer cells include decreased PARP1 trapping by PARP1 mutation and downregulation of PARG, and replication fork stabilization by loss of EZH2 and PTIP." (PMID 38625917, 2024). "Collectively, our data not only identify an essential role for PARG in normal proliferating cells but also provide a potential biomarker for the further development of PARG inhibitors in cancer therapy." (PMID 38578205, 2024). "In recent years, PARP and PARG inhibition has been explored to treat cancers with high levels of replication stress and genomic instability due to defective DNA repair." (PMID 38360994, 2024). "And, what are the implications for the development of predictive biomarkers to a priori identify cancer cells likely to be sensitive to PARG inhibitors?" (PMID 39015544, 2024). "Given the critical roles of PARG in the maintenance of the PARylation/dePARylation cycle in cells, PARG inhibitors have been developed recently as potential anti-cancer agents." (PMID 38578205, 2024). "The PARG inhibitor PDD00017273 provides beneficial fundamental insights into the function of PARG and its significance as a molecular target for cancer treatment." (PMID 36053937, 2023). "This underpins the finding of synthetic lethality between TARG1 and PARG, which is further exacerbated by HPF1 deficiency and reveals vulnerabilities in cancer cells." (PMID 37676774, 2023). "We believe that research on the mechanism of PARG inhibitor resistance is essential for comprehending the role of PARG in cancer and its anticancer drug target." (PMID 36053937, 2023). "This novel PARG inhibitor inhibits tumor cell growth in cell‐based and xenograft mouse cancer models." (PMID 36053937, 2023). "Decreasing pADPr levels through PARG overexpression has been shown to mitigate the malignant behavior of cancer cells and reduce cancer growth." (PMID 38139034, 2023). "Here, we examined the effects of PARP inhibitor olaparib, an approved anti-cancer agent, and PARG inhibitor PDD00017273 on osteoblast differentiation." (PMID 35563432, 2022). "We studied PARG RNA expression for different cancer types compare to corresponding normal tissue based on TCGA database." (PMID 35585513, 2022). "PARG inhibition has recently emerged as a promising approach in cancer treatment, particularly in combination with DNA-damaging agents or radiotherapy." (PMID 34019811, 2021). "To identify what genes that became misregulated in PNX0010 cells overexpressing PARG are known to be related to cancer growth, we applied our differently expressed genes to IPA software 2020 Fall release for “cancer” disease phenotype." (PMID 34638458, 2021). "This underlies the synthetic lethality between PARG and ARH3 in cancers and the development of neurodegeneration in ARH3/ADPRHL2-deficient patients." (PMID 34019811, 2021).